CTTN (cortactin)
Diseases named in the same sentence as CTTN in open-access papers (continued):
Sharing a sentence is not in itself a finding about the gene and the disease.
cancer (continued). "Increased cortactin deacetylation by HDAC6 overexpression in cancer cells provides further evidence for the role of HDAC6 in promoting cancer cell migration and invasion." (PMID 39941046, 2025). "CTTN has been shown to promote cancer development owing to its elevated expression, which is indicative of a poor prognosis." (PMID 39877290, 2025). "To then evaluate whether this differential distribution could be associated with differential cortactin expression and/or activation, we performed western blotting against total and phosphorylated cortactin on tyrosine residue 421, a pro-migratory event associated with cancer and poor prognosis." (PMID 38200575, 2024). "The expression of cortactin, another cancer-related actin regulator, was also correlated with poor survival in all subtypes although not statistically significant in TNBC only." (PMID 38353696, 2024). "Mechanistic investigations further demonstrate that TRPC5 promotes filopodia formation in gastrointestinal cancer cells via the ATP/p-MLC/p-cortactin signaling axis, unveiling a novel pathway driving cancer metastasis." (PMID 39309444, 2024). "Analysis using multiple databases revealed that TRPC5 plays a critical role in regulating cancer cell motility Subsequent experiments confirmed that TRPC5 enhances filopodia formation by activating the ATP/p-MLC/p-cortactin signaling axis." (PMID 39309444, 2024). "Cortactin is required for the assembly of protrusion in cancer cells and is important for cell migration and invasion." (PMID 37508480, 2023). "Other authors have established a relation between cortactin and vinculin overexpression and cancer aggression and resistance, and have also proposed them as promising prognostic and predictive biomarkers." (PMID 37686651, 2023). "Our data suggest that CTTN plays a crucial role in resistance to anti-cancer treatments such as chemotherapy and radiotherapy." (PMID 36831511, 2023). "Cortactin plays a central role in the development and maturation of invadopodia and drives the degradation of the extracellular matrix in invasive cancer cells." (PMID 37761244, 2023). "Both SAMHD1 and phosphorylated cortactin levels were higher in cancer tissues than in adjacent normal tissues." (PMID 37009792, 2023). "In the present study, NEK9 increased the total quantity and phosphorylation level of CTTN, which directly regulated cytoskeletal reorganization necessary for cancer cell movement." (PMID 37443302, 2023). "The effect of CTTN on cancer stem cell activity was assessed using the tumorsphere formation, ALDEFLUOR assay, and by in vivo xenograft experiments." (PMID 36831511, 2023). "Since hAM preparations strongly reduced the migration of cancer urothelial cells, we further investigated their effect on the expression of key components required for efficient cell migration, such as cortactin, RhoA, RhoC, Cdc42 and Rac1." (PMID 37932474, 2023). "Further, PRMT5/E2F1 expression and cortactin/CTTN expression showed positive correlations across different types of cancer in the Cancer Genome Atlas datasets (TCGA), suggesting that E2F1 and PRMT5 regulate the process of cell migration and invasion." (PMID 37795443, 2023). "Cortactin (CTTN) is an actin-binding protein that is mainly known for its ability to promote cancer progression." (PMID 36831511, 2023). "For further confirmation, we analyzed the correlation between SAMHD1 and cortactin phosphorylation in paired cancer and normal tissues from patients with ccRCC." (PMID 37009792, 2023). "CTTN overexpression-induced cancer stem cell-like characteristics in experiments of tumorsphere formation, ALDEFLUOR assays, and in vivo limiting dilution assays." (PMID 36831511, 2023). "CTTN-induced cancer stem cell-like properties were reversed by treatment of β-catenin/TCF inhibitor." (PMID 36831511, 2023). "Treatment of the β-catenin/TCF inhibitor reversed CTTN-induced cancer stem cell-like properties in vitro." (PMID 36831511, 2023).
cancer (continued). "It encodes cortactin, which serves as an F-actin-binding protein (ABP) and has been found to be overexpressed in human carcinomas as early as 1992." (PMID 37623256, 2023). "Some of these AASEs affect genes that are not only associated with immunity but also play essential roles in inflammation (e.g., FN1 and HYAL2) and cancer oncogenesis (e.g., CTTN, FN1, and DGKZ)." (PMID 35752626, 2022). "Previous studies have shown that FMNL2 binds directly many actin bundling proteins, such as fascin and cortactin, then facilitates cancer cell migration." (PMID 36335129, 2022). "CTTN enhances cell migration, invasion, and tumor cell metastasis and is overexpressed in many cancers, including HCC." (PMID 36557005, 2022). "CTTN can regulate intermolecular adhesions as well as cytoskeletal and cell adhesion structures that organize epithelial and cancer cells, which is relatively less researched." (PMID 36713541, 2022). "To gain insight how Cav2.2 decreased cortactin ubiquitination, we analyzed the correlation between the expression of cortactin and ubiquitin ligases or deubiquinating enzymes by using the proteomics data from Cancer Cell Line Encyclopedia (CCLE) database." (PMID 36137995, 2022). "Detection of invadopodia by observing colocalization of TKS5, an invadopodia marker in human cancer lines, and cortactin in the sections of tumor tissue revealed that knocking out YAP1 expression significantly decreased invadopodia formation." (PMID 35773411, 2022). "Among them, N-WASP and cortactin are essential components that can synergistically activate Arp2/3 complex, and these proteins are upregulated in malignant cancer cells." (PMID 35075179, 2022). "In fact, it was well demonstrated that cancer cells develop invadopodia and podosomes composed of structural proteins, such as cortactin, Tks4, and Tks5, to facilitate their migration across the endothelial layer to invade distant tissues." (PMID 35893033, 2022). "A different NSCLC study describes the role of CTTN and its binding partner dynamin in stimulating the formation of F-actin bundles, leading to filopodia formation and cancer cell migration." (PMID 35562995, 2022). "The positive staining of Hsp70, MMP14, MMP2, and cortactin was mostly observed in the cytoplasmic of the carcinoma cells, whereas the nucleic positive signals were detected much more in the Hif1α immunohistochemical staining." (PMID 35957827, 2022). "Overexpression of CTTN was reported by several cancers, including OSCC, and its expression enhanced cancer cell aggressiveness in OSCC." (PMID 34884487, 2021). "Given the importance of cortactin for invadopodia formation, cancer cell migration, and metastasis, we examined the mRNA expression levels and location of cortactin by qRT-PCR and immunohistochemical staining." (PMID 35178403, 2021). "We discovered that cortactin phosphorylated at Y-470 recruits the signaling factor Vav2 to activate the small Rho GTPase Rac1, and finally, a cancer cell motility phenotype." (PMID 34439396, 2021). "Last but not least, despite of insufficient evidence, some studies have reported how oncogenes, cytokines, and exosomes interacted with each other in cancer, as reported in a squamous cancer cell line that cortactin promotes exosome secretion." (PMID 34109113, 2021). "We aimed to study the molecular mechanisms of how the gastric pathogen Helicobacter pylori hijacks cortactin phosphorylation via tyrosine kinase Abl to trigger cancer-related signal transduction events." (PMID 34439396, 2021). "In particular, the importance of cortactin for invadopodia formation, cancer cell migration, and metastasis has been proven." (PMID 35178403, 2021). "In those cancer cells, LIF promoted invadopodia-associated characteristics and markers, such as tyrosine kinase substrate with five SH3 domains (TKS5), cortactin (CTTN), matrix metallopeptidase 2 (MMP2) and SRC proto-oncogene (SRC)." (PMID 34361105, 2021).
cancer (continued). "Invadopodia, forming cellular actin-based protrusions, is mediated by cortactin activation and accompanies the invasion of cancer cells to the mesenchymal layer." (PMID 33407452, 2021). "Cortactin has emerged not only as a crucial regulator of actin cytoskeletal dynamics, but also as a key player in aggressive cancers (McGrath and Koleske., 2012)." (PMID 33773540, 2021). "Tyrosine 397 phosphorylation allows interactions between FAK and proteins regulating cancer cell migration and invasion, such as Src, cortactin and PI3K." (PMID 31986121, 2020). "From a clinical perspective, these results support the application of cortactin as a promising therapeutic target for diseases such as cancer." (PMID 33195233, 2020). "Cortactin/CTTN is a gene of significant interest in cancer cell invasion and migration because of its role as a crucial regulator of actin cytoskeletal dynamics and it’s overexpression in aggressive cancers." (PMID 32709847, 2020). "SHANK2 and CTTN are co-amplified in several cancers, these proteins interact functionally together and are involved in cell motility." (PMID 32252688, 2020). "Cortactin is abundantly localized in invadopodia structures of invasive cancer cells due to its role in the regulation of enzymes involved in ECM degradation, such as MMPs." (PMID 31986121, 2020). "In these cancer cells, invadopodium precursors recruit MenaINV (an isoform of mammalian Ena protein), which promotes phosphorylation of cortactin at Y-421." (PMID 31936446, 2020). "In cancer cells, disruption of cortactin, which is a major component in invadopodia, impaired invadopodia-mediated ECM degradation." (PMID 32678085, 2020). "In cancer cells, cortactin plays a crucial role in formation of invadopodia as well as secretion of MMPs30." (PMID 32678085, 2020). "Due to its role in cell migration and invasion, cortactin is associated with various types of cancers, and overexpression of cortactin is used as a biomarker for cancer progression." (PMID 31940955, 2020). "In all three cancer types, there was a similar high expression of cortactin/CTTN in tumour relative to normal tissue." (PMID 32709847, 2020). "In cancer cells, invadopodia are detected as protrusions enriched for both actin and cortactin—a regulator of actin polymerization." (PMID 32678085, 2020). "Cortactin has been considered as an invadopodial marker, as the ability of cancer cells to form invadopodia is often correlated with their invasive and metastatic capabilities." (PMID 33614634, 2020). "In particular, Meta4 organoids continuously expressed Cortactin, which has critical roles for cancer cell invasion and migration, through many rounds of passaging." (PMID 31804471, 2019). "The nucleation-promoting factor cortactin is expressed and promotes tumor progression and metastasis in various cancers." (PMID 30976201, 2019). "In our and others’ previous work, Src activated Stat3 and FAK/cortactin signaling and promoted migration and invasion of cancer cells." (PMID 31731716, 2019). "Amongst them, we found particularly striking the strong KRT80-dependent induction of cortactin (CTTN), a factor directly linked to actin rearrangements, lamellipodia formation and cancer cell invasion, that we confirmed by immunofluorescence." (PMID 31073170, 2019). "In contrast to other HDACs, HDAC6 regulates the acetylation of non-histone proteins such as α-tubulin, β-catenin, cortactin, and heat shock protein 90 and participates in cancer development and progression." (PMID 30594243, 2018).
cancer (continued). "All these reports indicated that cortactin plays an important role on tumor invasion and is subject to regulation by microRNAs, which indicates that the mechanism of cortactin involved in cancer cell progression and invasion are complicated and obscure." (PMID 29986736, 2018). "To test the effects of Myc B on actin regulatory proteins, we visualized the changes in localization of the F-actin binding protein Cortactin that functions in cancer cell motility and invasion." (PMID 30467396, 2018). "A review showed that CTTN plays an important role in migration and invasion in both normal and cancer cells." (PMID 30220969, 2018). "High cortactin expression is associated with cell motility, invasion, and metastasis, and the elevated expression of cortactin correlates with the poor prognosis in human carcinomas." (PMID 29678203, 2018). "Cortactin promotes cancer cell migration and invasion, and plays a pivotal role in invadopodia formation and extra cellular matrix degradation." (PMID 29152154, 2017). "In this review, we report on the current knowledge and potential mechanisms of action of cortactin as a critical mediator of cancer cell migration and invasion." (PMID 29152154, 2017). "Cortactin, a substrate of sarcoma (Src) kinases, is an actin-binding protein that is involved in cytoskeletal regulation, and is frequently overexpressed in cancer cells." (PMID 29152154, 2017). "Similar as in many cortactin regulatory mechanisms, acetylation appears to play an essential role in the cancer progression." (PMID 29152154, 2017). "We observed that CTTN promotes cancer cell proliferation in vitro and increases CRC tumor xenograft growth in vivo." (PMID 27903975, 2017). "For example, in invadopodia, the disruption of tyrosine phosphorylation sites of cortactin prevented cell edge protrusion, cancer cell invasion, and actin polymerization." (PMID 29152154, 2017). "It has been proved that cortactin protein as well as tyrosine phosphorylation of itself which has been reported to enhance cancer cell motility were expressed at high levels in CRC and associated with poor prognosis." (PMID 28404950, 2017). "CTTN is overexpressed in many tumors, across several cancers: head and neck, gastric, hepatocellular, and colorectal." (PMID 27903975, 2017). "Here, we provide an overview of the roles of cortactin, emphasizing the interaction with the actin cytoskeleton as well as the roles of cancer cell migration and invasion." (PMID 29152154, 2017). "CTTN promotes cancer cell mobility, and Timpson's research suggested CTTN inhibited EGFR ubiquitination and degradation in HNSCC." (PMID 27903975, 2017). "Mutation of PBF (Y174A) or pharmacological intervention modulates the PBF: CTTN interaction and attenuates the invasive properties of cancer cells." (PMID 27603901, 2016). "Our study identified that PBF and CTTN physically interact and co-localize, and that this occurs at the cell periphery, particularly at the leading edge of migrating cancer cells." (PMID 27603901, 2016). "Invadopodia are specialized F-actin and cortactin-rich membrane protrusions formed at the ventral surface of highly aggressive cancer cells, including MDA-MB-231, and display local proteolytic activity towards extracellular matrix constituents." (PMID 27042827, 2016). "AFAP1L1 was shown to play a role in tumour metastasis and to constitute a cancer prognostic marker, to be localised to invadosomes and along with cortactin, to podosomes." (PMID 25875301, 2015). "A sharp increase of cortactin mRNA under hypoxic conditions at 24 h revealed a possibility that the cancer cells in a hypoxic tumour microenvironment appear to be able to resistant to CBF." (PMID 26134506, 2015). "The expressions of levels of cortactin, an important factor in tumour progression and cancer invasion, were assessed in in vitro and in vivo experiments." (PMID 26134506, 2015). "The phosphorylated form of cortactin (pTyr421) plays major role in cancer cell migration and invasion." (PMID 25566531, 2014).
cancer (continued). "We first analyzed cortactin mRNA expression in 81 frozen colon tissue samples, which included 37 normal tissues, 5 benign, and 39 malignant tumors, by quantitative RT-PCR." (PMID 24465712, 2014). "Cortactin (cortical actin binding protein or CTTN, a monomeric protein located in the cytoplasm of cells), encoded by the CTTN/EMS1 gene, is a v-Src substrate localized with cortical actin at the plasma membrane and is up-regulated in several types of cancer." (PMID 25566531, 2014). "Based on current knowledge from clinical and basic research studies, cortactin appears to be an attractive target for modulation due to its overexpression in cancer, and its prominent role in cell motility." (PMID 24465712, 2014). "One well-defined mechanism determining aberrant migration of cancer cells is mediated by elevated levels of phosphorylated cortactin, which is triggered by Src and other kinases." (PMID 24465712, 2014). "Cortactin, encoded by the CTTN/EMS1 gene, is a v-Src substrate localized with cortical actin at the plasma membrane and is overexpressed in many types of cancer." (PMID 24465712, 2014). "For the purpose of this study, we focused on the decreased levels of cortactin in response to curcumin treatment, because it is frequently overexpressed in cancers and it has been reported to enhance tumor cell migration and invasion." (PMID 24465712, 2014). "Cortactin is a well-established organizer of the cortical actin cytoskeleton at the leading edge to promote motility and invasiveness of cancer cells." (PMID 24086576, 2013). "The potential role of CORTACTIN as prognostic biomarker has been previously investigated in different types of cancer." (PMID 23423155, 2013). "Human cortactin is encoded by CTTN (formerly EMS1) on chromosome 11q13, which is often amplified in various cancers, such as breast, head and neck." (PMID 23991004, 2013). "Numerous reports have shown the overexpression of regulators and/or component proteins of the invadopodia, including cortactin and Tks5 in highly invasive cancer cells." (PMID 23991004, 2013). "A number of studies investigated the role of cortical actin-binding protein (CORTACTIN) as prognostic marker in different types of cancer." (PMID 23423155, 2013). "The mlt protrusions are enriched in the invadopodia proteins Actin, Cortactin, and Src, and their formation requires Tks5, a Src substrate required for invadopodia formation in cancer cells." (PMID 22973180, 2012). "In a similar scenario, knockdown of cortactin in carcinoma cells resulted in decreased matrix degradation ability of the podosome-related invadopodia." (PMID 22514729, 2012). "During cancer cell invasion, cortactin is one of the proteins that direct actin bundles to form invadopodia." (PMID 22078467, 2011). "Cortactin is frequently overexpressed in malignant tumors and there is a correlation between cortactin phosphorylation and enhanced cell migration and metastasis." (PMID 22078467, 2011). "The GEP100-Arf6-AMAP1-cortactin pathway, activated by receptor tyrosine kinases, appears to be common in angiogenesis and cancer invasion and metastasis, and provides their new therapeutic targets." (PMID 21858086, 2011). "The localization of pS418 cortactin in carcinoma lamellipodia and invadopodia is consistent with the defined and emerging roles cortactin plays in regulating actin dynamics within these structures." (PMID 21079800, 2010). "Expression of S405A, S418A or S405,418A cortactin resulted in an 49% average decrease in cell migration for each cortactin mutant compared to Ctl, indicating that phosphorylation of S405 and S418 are vital in maintaining optimal carcinoma cell motility." (PMID 21079800, 2010). "Cortactin (CTTN), which is often over-expressed in HNSCCs and helps organize the cytoskeleton and cell adhesion structures of epithelia and carcinoma cells, is 14-fold up-regulated." (PMID 20174472, 2010).